APLN (apelin)
Diseases named in the same sentence as APLN in open-access papers (continued):
Sharing a sentence is not in itself a finding about the gene and the disease.
Hypertension (68 papers, 2010 to 2025). The presence of chronic increased pressure in the systemic arterial system. "The results of a meta-analysis study showed that lowering the circulating apelin level was significantly associated with an increased risk of hypertension." (PMID 40299338, 2025). "Apelin has been confirmed to be strongly associated with the occurrence and development of hypertension, and apelin and APELA share the APJ and exhibit a similar cardiovascular profile." (PMID 35630008, 2022). "It is noteworthy that the apelin gene is located on the X chromosome, and there are sex‐specific genetic polymorphisms of both apelin and its receptor that confer differing risks of hypertension." (PMID 35748053, 2022). "Apelin was studied in diabetes, insulin resistance and hypertension and it was reported to be negatively associated with hypertensive heart disease." (PMID 30864627, 2019). "By direct sequencing, the initial family-based association study has identified 5 common polymorphisms in apelin/APJ system associated with hypertension." (PMID 27863393, 2016). "MicroRNAs are linked with modulation of the ACE2/Apelin signaling, which exhibits beneficial effects in the cardiovascular system and hypertension." (PMID 25815211, 2015). "Our findings provided strong evidence for the genetic involvement of apelin/APJ pathway in susceptibility to hypertension." (PMID 23226564, 2012). "Recently, Li and his colleagues have assessed the associations of polymorphisms within APLN with essential hypertension in a family-based study and reported a positive result." (PMID 23316219, 2012). "Apelin and its receptor help to stimulate hematopoiesis in embryonic stem cells, and dysregulation of these genes is linked to numerous disorders related to blood flow problems and hypertension." (PMID 24555763, 2014). "However, other studies conducted on normotensive Sprague Dawley rats treated with angiotensin II to induce hypertension showed that daily administration of apelin was unable to reduce the BP elevation caused by angiotensin II or the harmful effects, such as cardiac hypertrophy and fibrosis." (PMID 41515992, 2025). "In the current study, the apelin-dependent effects on blood pressure were analyzed during vascular endothelial dysfunction, the most common predisposing factor in various cardiovascular diseases, including hypertension, thrombus, stroke, renal failure and cardiac failure." (PMID 23525196, 2013). "Administration of pyr1-apelin-13 prevented the progression of Ang II-mediated hypertension, cardiac hypertrophy, fibrosis, and dysfunction in mice with elevated ACE2 levels." (PMID 41155377, 2025). "This is consistent with experimental data showing Apelin’s ability to enhance endothelial function and reduce hypertension." (PMID 39859178, 2025). "A decreased concentration of apelin has been observed in patients with arterial hypertension aggravated by left ventricular hypertrophy, as well as those with ischemic heart disease." (PMID 40943120, 2025). "The RAAS plays a key role in hypertension-induced cardiac remodeling, and apelin has been identified as a counter-regulator of ANG II-mediated effects." (PMID 40362262, 2025). "Studies conducted in rats with LNAME-induced hypertension or unilateral renal artery obstruction showed a decrease in both apelin and APLNR levels in cortical and medullar kidney extracts." (PMID 39200188, 2024). "In hypertensive overweight/obese children, Lep and APLN levels were found to be statistically higher than normal controls and NW subjects with hypertension." (PMID 37240998, 2023). "The reduced levels of key vasodilatory adipokines, specifically apelin and relaxin, play a critical role in modulating vascular tone, potentially leading to hypertension." (PMID 37799258, 2023).
Hypertension (continued). "In this regard, it has been reported that administration of either apelin or ELA had a blood pressure-lowering effect, potentially indicating a therapeutic role of these peptides in reverting hypertension, thus reducing the risk of developing HF." (PMID 37242650, 2023). "Apelin/APJ system induces hypertension via affecting sympathetic nervous system, renin–angiotensin–aldosterone system, endothelial injury, excessive endothelin, sodium retention and vascular remodeling." (PMID 35831335, 2022). "The peripheral apelinergic system appears to be down-regulated in hypertensive disease, with changes in the levels of both immunoreactive (ir)-APJ and/or apln/apelin in human and some rodent hypertension models." (PMID 34421653, 2021). "Apelin treatment has been proven beneficial for conditions as diverse as hypertension, atherosclerosis, myocardial infarction, and other cardiovascular diseases." (PMID 32849850, 2020). "Apelin mRNA expression increased by approximately 40% in hypertensive rats in response to swimming training for 9 weeks, and had positive effects on hypertension." (PMID 33019579, 2020). "In brief, apelin is an anti-aging factor and has positive effects on hypertension and ischemia-reperfusion injury when combined with exercise." (PMID 33019579, 2020). "On the other hand, in chronic reno-vascular hypertensive rats a reverse relationship was found between inotropic effects of apelin and APJ/KOR heterodimerization." (PMID 30627376, 2018). "Apelin treatment substantially reduced cardiac hypertrophy in rodents with heart pressure overload and various models of hypertension." (PMID 30286717, 2018). "To shed more light on this issue, we decided to interrogate the gender-specific association of 5 well-defined polymorphisms in apelin/APJ system with both blood pressure changes and hypertension risk in a northeastern Chinese population." (PMID 27863393, 2016). "This is a replication study interrogating the association of five well-defined polymorphisms in apelin/APJ system with blood pressure changes and hypertension risk in a northeastern Chinese population." (PMID 27863393, 2016). "This suggests a role for decreased peripheral apelin signalling in the pathophysiology of hypertension." (PMID 27492965, 2016). "The aim of this study was to interrogate the gender-specific association of 5 well-defined polymorphisms in apelin/APJ system with both blood pressure changes and hypertension risk in a northeastern Chinese population." (PMID 27863393, 2016). "In light of these observations, it would be tempting to postulate that genetic mutation of apelin/APJ system can regulate blood pressure and result in the development of hypertension." (PMID 27863393, 2016). "It is widely accepted that apelin/APJ system plays a crucial role in angiogenesis, a pathological hallmark of hypertension." (PMID 27863393, 2016). "To deepen our understanding on the genetic contribution of apelin/APJ system, we investigated the association of 5 well-defined polymorphisms with both blood pressure changes and hypertension risk among 650 hypertensive patients and 645 normotensive controls." (PMID 27863393, 2016). "In spite of the null association of apelin gene with hypertension in this study, we observed that SBP differed significantly between two homozygous genotypes of rs3761581 in apelin gene." (PMID 27863393, 2016). "Given that the genes coding for apelin and APJ are polymorphic, it is crucial to identify genetic defects in apelin/APJ system that are responsible for blood pressure regulation and determine an individual's risk for developing hypertension." (PMID 27863393, 2016). "In this review, we focus on the relationship among the ACE2/Apelin signaling, miRNAs, and hypertension and aim to facilitate the exploitation of new therapeutic medicine to control hypertension." (PMID 25815211, 2015).
Hypertension (continued). "The ACE2-coupled crosstalk among the RAAS, the Apelin system, and microRNAs provides an important mechanistic insight into hypertension." (PMID 25815211, 2015). "Apelin also protects wild type mice against AngII-induced hypertension and cardiovascular fibrosis via direct regulation of PAI-1 gene expression." (PMID 26342945, 2015). "Intriguingly, recent studies have demonstrated that there is a link between the ACE2/Apelin signaling and microRNAs (miRNAs) in the pathogenesis of hypertension." (PMID 25815211, 2015). "Although hypertension, as an independent predisposing factor, perpetuates CAD, our results supported a small to moderate contribution of apelin/APJ pathway to the development and progression of CAD among hypertensive patients." (PMID 23226564, 2012). "First, this study was based on our previous findings linking the top polymorphic markers of apelin/APJ pathway to hypertension and its related phenotypes, and inclusion of genetic markers were biologically plausible." (PMID 23226564, 2012). "Reduced circulating levels of apelin have been demonstrated in the patients with essential hypertension." (PMID 22655211, 2012). "Genetic variation in apelin likely contributes to essential hypertension and the onset of aged hypertension." (PMID 22655211, 2012). "In accord with this, circulating apelin was reported to be decreased in patients with essential hypertension, suggesting an important role for the apelin/APJ system in human blood pressure regulation." (PMID 23316219, 2012). "A more recently discovered adipocytokine, apelin, is predominantly expressed in the ECs of the heart and support a role for apelin in the development of hypertension and cardiac hypertrophy." (PMID 20509943, 2010). "Additionally, apelin’s ability to counteract ANG II-mediated damage underscores its significance in mitigating hypertension-induced cardiac remodeling." (PMID 40362262, 2025). "This contrasting functionality immediately suggests a potential counter-regulatory relationship, where dysfunction in apelin signaling could exacerbate pathological processes driven by Ang II in hypertension, a key factor in HHD development." (PMID 40362262, 2025). "In contrast, both apelin and its receptor were markedly reduced in SHRs, likely due to the genetic, chronic nature of SHRs hypertension versus the acquired, secondary nature of 2K1C hypertension." (PMID 40362262, 2025). "In individuals with hypertension both apelin, elabela, and apelin receptor are underexpressed." (PMID 40943120, 2025). "Overall, the apelin system is altered in hypertension and is a potential therapeutic target." (PMID 37956047, 2023). "The apelin/ELA-APJ system can affect hypertension counteracting RAS." (PMID 37242650, 2023). "The interplay of reduced apelin and relaxin levels may significantly contribute to heightened vascular tone and hypertension, emphasizing their potential as therapeutic targets for vascular health management." (PMID 37799258, 2023). "Furthermore, reduced levels of vasodilatory adipokines, apelin, and relaxin can lead to increased vascular tone and hypertension." (PMID 37799258, 2023). "Given the BP-lowering effect of apelin, targeting the ApelinR may constitute a potential approach for the treatment of hypertension." (PMID 34393794, 2021). "Understanding the central circuitry through which systemic apelin affects central cardiovascular responses will increase our understanding of the pathogenesis of hypertension and aid in elucidating the therapeutic potential of the apelinergic pathway in a hypertensive disease state." (PMID 34421653, 2021). "A meta-analysis has reported lower plasma apelin concentrations in patients with hypertension." (PMID 34393794, 2021). "Elevated maternal plasma apelin values may come from a source other than the placenta, such as fat tissue, or be a response to elevated vascular resistance or hypertension induced by factors other than apelin." (PMID 34577885, 2021).
Hypertension (continued). "Importantly, Elabela was more effective than Apelin-13 in reducing high blood pressure, cardiovascular and renal dysfunctions, fibrosis and hypertrophy in high-salt fed SHR." (PMID 34385922, 2021). "ACE2 in turn is able to regulate apelin bioavailability, establishing a negative feedback loop, and the crosstalk between RAAS, ACE2 and Apelin system might play a significant role in the pathophysiology of hypertension." (PMID 33195436, 2020). "However, although apelin has been thought to contribute to the establishment of hypertension, the importance of the apelinergic system in influencing SNA and arterial BP is unclear." (PMID 30459635, 2018). "Dysfunction of the apelinergic system, comprised of the neuropeptide apelin mediating its effects via the G protein-coupled apelin receptor (APJ), may underlie the onset of cardiovascular disease such as hypertension." (PMID 30459635, 2018). "Future research about the effect of apelin in patients with hypertension should focus on the mechanism in addition to the NO pathway in order to find hidden side effects of apelin in patients with hypertension in further clinical studies." (PMID 29302260, 2017). "There is strong evidence that apelin/APJ system is a promising therapeutic target for hypertension." (PMID 27863393, 2016). "The crosstalk between the ACE2/Apelin signaling and miRNAs provides an important mechanistic insight into hypertension and may lead to the development of new therapeutic regimens." (PMID 25815211, 2015). "In this study, we enrolled patients with essential hypertension (EH) and found that serum apelin is closely associated with the prevalence of LVH in these patients, suggesting serum apelin may be used as a marker to predict the LVH prevalence." (PMID 26342945, 2015). "Although global scientists have conducted exhaustive research regarding the functional aspects of apelin/AGTRL1 system, data are relatively sparse on the association of multiple genetic defects in this system with hypertension and related diseases in current literature." (PMID 24465893, 2014). "AGTRL1 and apelin are highly expressed in cardiovascular system, and they are believed to play an important role in counter-regulating the effect of renin-angiotensin system, a classical pathway leading to hypertension." (PMID 24465893, 2014). "Finally, due to its importance in apelin-mediated hypertension, APJ expression in the aorta was examined using RT-PCR." (PMID 23525196, 2013). "Via sequencing the genes of apelin/angiotensin receptor-like 1 (apelin/APJ) pathway, we have recently identified and validated four common polymorphisms (rs3761581, rs56204867, rs7119375, and rs10501367) implicated in the development of hypertension." (PMID 23226564, 2012). "Notably, ELA and apelin circulating levels were found decreased in patients with hypertension." (PMID 37242650, 2023). "Interestingly, normotensive children of hypertensive parents have been reported to exhibit hyposecretion of vasodilatory adipokines, such as apelin and relaxin, which may further contribute to the pathophysiology of hypertension in this population." (PMID 37799258, 2023). "However, apelin-13 may conduct vasoconstriction and deteriorate hypertension in rats after harming the vascular endothelium." (PMID 29302260, 2017). "The multifaceted roles of the apelin/APLNR system in cardiovascular regulation and its dysregulation in hypertension and heart failure make it an attractive therapeutic target for HHD." (PMID 40362262, 2025). "The apelin/ELABELA-APJ axis can represent a potential HF therapeutic target and has been shown to play a role in the pathophysiology of both MI and hypertension." (PMID 37242650, 2023). "Previous studies have reported that apelin promotes collagen deposition and increases the expression of MMP-2 or MMP-9 in overnourished mice or rats with hypertension-induced left ventricular hypertrophy." (PMID 31829402, 2019).
Hypertension (continued). "Both ACE2 and Apelin exhibit beneficial effects in the cardiovascular system, and recombinant ACE2 has recently been shown as a candidate therapeutic for treating hypertension in animal models." (PMID 25815211, 2015). "Considering the close mechanistic relationship between apelin/AGTRL1 system and the renin-angiotensin system, it is logical to make AGTRL1 gene as a candidate gene for hypertension." (PMID 24465893, 2014). "Therefore, the effect of interaction between AGTRL1 and APLN on hypertension remained unknown." (PMID 23316219, 2012). "Moreover, hypertension-induced heterodimerization of APLNR and kappa-opioid receptor was normalized by apelin administration, further illustrating the intricate molecular interplay between these pathways." (PMID 40362262, 2025). "Chronic vascular exposure to damage (e.g., prolonged hypertension) may reduce ELA and apelin synthesis/secretion by dysfunctional endothelium, weakening apelinergic protection in chronic CAD." (PMID 41155377, 2025). "Collectively, unexpected results from this study demonstrate that the chronic administration of apelin did not reduce either the blood pressure or Ang II-induced hypertension, cardiac hypertrophy, and cardiac fibrosis." (PMID 37111357, 2023). "Moreover, AngII lowered apelin and ELA levels in both rat and primary neonatal rat cardiac fibroblasts, and these results were in line with the low level of these peptides in hypertension patients." (PMID 37242650, 2023). "Apelin and APJ mRNA expression levels were reduced in rats with hypertension, which correlates with the significantly lower level of plasma apelin in the group of newly diagnosed hypertensive patients." (PMID 29875677, 2018). "The involvement of the apelin–APJ system in hypertension has been studied extensively in the past few years, nevertheless, in the setting of hypertensive patients with LVH, there is little knowledge about the role of apelin." (PMID 26342945, 2015). "Apelin levels were reduced in patients with essential hypertension independent of left ventricular systolic and diastolic dysfunction." (PMID 25815211, 2015). "In conclusion, we have reported that serum apelin level is strongly and independently related to LVH in a population with essential hypertension, suggesting that this peptide may be used as a biomarker of LVH." (PMID 26342945, 2015). "However, our chronic studies in conscious animals are in agreement with our acute results in anesthetized rats, indicating no contribution of endogenous apelin in the RVLM to hypertension via activation of SNA and MABP." (PMID 30459635, 2018). "Thus, apelin activation of APJ does not appear to have a role to play in the genesis or maintenance of hypertension in the animal models used in this study." (PMID 30459635, 2018). "Additionally circulating levels of apelin are decreased in patients with essential and pulmonary hypertension, while there is a negative correlation between plasma apelin levels and blood pressure." (PMID 27492965, 2016). "The Apelin/APJ system has been shown to be involved in a wide range of pathophysiology effects in cardiovascular system, which is a necessary process in the initiation and development of various cardiovascular diseases such as pulmonary hypertension and essential hypertension." (PMID 25815211, 2015). "Therefore, phosphorylated ERK may have not mediated the inotropic response of apelin in reno-vascular hypertensive rats." (PMID 30627376, 2018). "The attenuation of apelin expression and function in rostral ventrolateral medulla (RVLM) neurons, which represents the major source of excitatory output to sympathetic preganglionic neurons, might be a central pathway involved in antihypertensive effects of EA on stress-induced hypertension." (PMID 28293268, 2017).
Hypertension (continued). "Since apelin presumably does not cross the BBB (although this has been disputed, and may change in hypertension), the CVOs are likely important conduits allowing circulating apelin access to the brain." (PMID 32315363, 2020).